IGFBP3 (insulin like growth factor binding protein 3)
Diseases named in the same sentence as IGFBP3 in open-access papers (continued):
Sharing a sentence is not in itself a finding about the gene and the disease.
gastric cancer (19 papers, 2005 to 2023). A primary or metastatic malignant neoplasm involving the stomach. "Genetic variants of IGFBP3 were found to correlate significantly with the survival of patients affected by advanced gastric cancer (GC), which is the most frequent cause of cancer-related mortality." (PMID 30111747, 2018). "Functional IGFBP3 SNPs (rs2854744 and rs2960436) determining high IGFBP3 circulating levels were associated with favorable prognosis of patients with advanced gastric cancer receiving palliative chemotherapy." (PMID 24386080, 2013). "Heritable polymorphisms in COX2 and in IGFBP3 have been reported to affect the risk of developing gastric cancer." (PMID 21194482, 2010). "Our previous report revealed that insulin-like growth factor binding protein-3 (IGFBP3) was regulated by HoxD10 in gastric cancer cells; however, the functional roles and underlying mechanisms of IGFBP3 in gastric cancer remain unclear." (PMID 24386080, 2013). "A study revealed that compared with healthy subjects, the level of serum IGFBP3 in patients with gastric cancer decreased significantly." (PMID 36409444, 2022). "Expression of IGFBP3/4/7 was significantly elevated in gastric cancer samples, whereas IGFBP1 expression was decreased in normal tissues." (PMID 34745945, 2021). "HOXD10 has been demonstrated to act as a transcription factor targeting the promoter region of IGFBP3 in gastric cancer." (PMID 29075359, 2017). "Overexpression of IGFBP-3 resulted in significant inhibition of total and phosphorylated RelA and IκB-proteins in gastric cancer cells and in reduced expression of NF-κB-regulated cell adhesion molecules, ICAM-1 and VCAM-1." (PMID 28350359, 2017). "Both HoxA13 and IGFBP-3 were overexpressed significantly in human gastric cancer specimens of Taiwan and The Cancer Genome Atlas." (PMID 27144338, 2016). "By scoring expression levels (0 to 7) by positivity and intensity of IHC staining, HoxA13 and IGFBP-3 were highly expressed (score ≥ 4) in 63.2% (36/57) and 28.6% (8/28), respectively, of these gastric cancer specimens." (PMID 27144338, 2016). "In gastric cancer, IGFBP-3 has been reported to be a suppressor of migration, invasion, and the EMT through suppression of invasive factors including MMP14 and urokinase-type plasminogen activator." (PMID 27144338, 2016). "We also analyzed HoxA13 and IGFBP-3 expression using the gastric cancer data of The Cancer Genome Atlas and found that both genes were overexpressed." (PMID 27144338, 2016). "Increased expression of HoxA13 (63.2%) and IGFBP-3 (28.6%) was detected in human gastric cancer tissues and was found in the gastric cancer data of The Cancer Genome Atlas." (PMID 27144338, 2016). "As expected, the expression level of IGFBP3 mRNA and protein were upregulated by forced expression of HoxD10 in different gastric cancer cell lines." (PMID 24386080, 2013). "IGFBP3 inhibits the migration and invasion of gastric cancer cells, at least in part, through the MMP14 and uPA/uPAR pathways." (PMID 24386080, 2013). "Genome-wide analysis revealed that multiple genes including IGFBP3 were regulated by HoxD10 in gastric cancer cells in our previous study." (PMID 24386080, 2013). "Knockdown of IGFBP3 accelerated gastric cancer cell migration and invasion and induced the expression of invasive factors including MMP14, uPA and uPAR." (PMID 24386080, 2013). "Elucidation of this network would provide further insights into the role of IGFBP3 in gastric cancer." (PMID 24386080, 2013). "To further identify the role of IGFBP3 in the metastasis of gastric cancer, we evaluated its role in modulating the migration and invasion of gastric cancer cells." (PMID 24386080, 2013). "Our studies provided first evidence to show that HoxD10 directly binds the IGFBP3 promoter to activate the expression of IGFBP3 in gastric cancer cells." (PMID 24386080, 2013).
gastric cancer (continued). "To evaluate the functional role of IGFBP3 in gastric cancer, we investigated the cell migration and invasion after knockdowning IGFBP3 in vitro." (PMID 24386080, 2013). "We further analyzed the correlation between the expression of IGFBP3 and the overall survival of gastric cancer patients." (PMID 24386080, 2013). "Here, we found that the expression of IGFBP3 were upregulated after ectopic expression of HoxD10 in gastric cancer cells." (PMID 24386080, 2013). "Collectively, above results indicate that IGFBP3 is a direct target of HoxD10 in gastric cancer cells." (PMID 24386080, 2013). "The expression of IGFBP3 is related to less metastasis and favors the survival of gastric cancer patients." (PMID 24386080, 2013). "The mRNA levels of MMP14, uPA and uPAR were uprequlated after knockdown of IGFBP3 in gastric cancer cells." (PMID 24386080, 2013). "Large populations and prospective studies were allowed to evaluate the potential utility of IGFBP3 as a biomarker of the progression of gastric cancer." (PMID 24386080, 2013). "Methylation of the IGFBP3 promoter is found in 67% of gastric cancers, and its silencing is predicted to increase tumor aggressiveness." (PMID 21194482, 2010). "Using IHC, IGFBP3 was found to be overexpressed in gastric cancers relative to the normal gastric tissue." (PMID 21092330, 2010). "IGFBP3 is thought to reduce gastric cancer metastasis by sequestering IGFs to prevent them from triggering receptor tyrosine kinases." (PMID 21194482, 2010). "All these studies illustrate the complex relationship between IGFBP3 and gastric cancer." (PMID 34745945, 2021). "HOXD10 targeted the IGFBP3 gene promoter region and upregulated its expression in gastric cancer." (PMID 29075359, 2017). "IGFBP-3 may potentiate gastric cancer cell division and invasion that contradicts previous findings of its role as a tumor suppressor." (PMID 27144338, 2016). "We also identified the IGFBP-3 as the target of HoxA13 and a positive regulator of gastric cancers." (PMID 27144338, 2016). "Knock-down of IGFBP-3 has also been shown to accelerate gastric cancer cell migration and invasion." (PMID 26370590, 2015). "Functionally, IGFBP3 could suppress the migration and invasion of gastric cancer cells, at least in part, through the regulation of those invasive factors, including metalloproteinase-14 (MMP14) and urokinase-type plasminogen activator (uPA)." (PMID 24386080, 2013). "In addition, the expression level of IGFBP3 is frequently downregulated in gastric cancer tissues and related to the overall survival, suggesting that IGFBP3 plays an important role in gastric cancer progression." (PMID 24386080, 2013). "Taken together, these data suggested that HoxD10 could transcriptionally upregulate the expression of IGFBP3 in gastric cancer cells." (PMID 24386080, 2013). "Considering promoter region of IGFBP3 has several potential binding sites for HoxD10, predicted by PROMO, a program for the prediction of transcription factor binding sites, HoxD10 might directly interplay with IGFBP3 in the regulation of gastric cancer cell invasion." (PMID 24386080, 2013). "To determine whether HoxD10 could transcriptionally regulate the expression of IGFBP3 in gastric cancer cells, we observed the expression level of IGFBP3 after stably introducing HoxD10 gene into BGC823 and SGC7901 cells, or transiently knocking down of HoxD10 in HGC27 cells." (PMID 24386080, 2013). "Thus, our data suggest that HoxD10-targeted gene IGFBP3 may suppress gastric cancer cell invasion and favors the survival of gastric cancer patients." (PMID 24386080, 2013). "We have systematically screened the potential targets of HoxD10 by cDNA microarray and identified multiple genes, including insulin-like growth factor binding protein-3 (IGFBP3) that might be responsible for the tumor suppressing effect of HoxD10 in gastric cancer." (PMID 24386080, 2013).
gastric cancer (continued). "Expression levels of IGFBP3, IGFBP4, and IGFBP7 were significantly elevated in gastric cancer tissues, whereas those of IGFBP1 were reduced in normal tissues." (PMID 34745945, 2021). "That is, IGFBP3, IGFBP4, and IGFBP7 expression levels were higher in gastric cancer patients vs. normal in the Oncomine data." (PMID 34745945, 2021). "Similar to GKN1, insulin-like growth factor binding protein-3 (IGFBP-3) is a potent tumor suppressor, which is down-regulated in gastric cancer." (PMID 28350359, 2017). "We identified both IGFBP-3 and HOTTIP are the target genes of HoxA13 in gastric cancer." (PMID 27144338, 2016). "In the present study, we identified that HoxD10 could directly bind the promoter regions of IGFBP3 potentially via the TTAT element, thus transcriptionally regulates its expression in gastric cancer." (PMID 24386080, 2013). "Thus, we analyzed the gastric cancer samples instead (esophageal cancer sample are also not available), and we found that IGFBP3 showed no prognostic value in gastric cancer." (PMID 36409444, 2022). "A study of 11 gastric cancer cell lines demonstrated that IGFBP1 expression levels were extremely low in all cell lines, whereas IGFBP2 and IGFBP4 were expressed in 10 and 9 cell lines, respectively, and IGFBP3, IGFBP5, and IGFBP6 were expressed in half of all cell lines." (PMID 34745945, 2021). "To figure out the possible mechanisms of how IGFBP3 regulate the invasiveness of gastric cancer cells, we examined the mRNA levels of MMP2/MMP7/MMP9/MMP14, TIMP1/TIMP2, uPA and its receptor uPAR, all of which are invasion-related factors, especially in gastric cancer." (PMID 24386080, 2013).
Stroke (17 papers, 2016 to 2026). Sudden impairment of blood flow to a part of the brain due to occlusion or rupture of an artery to the brain. "Plasma concentrations of IGF-1 and the ratio of IGF-1/IGFBP-3 have been under clinical evaluation for their association with vascular diseases, i.e., age related cognitive status and stroke recovery." (PMID 36770687, 2023). "Circulating IGFBP3 (insulin-like growth factor binding protein 3) levels are positively associated with BP, stroke, carotid atherosclerosis and risk factors for several cardiovascular diseases." (PMID 35345488, 2022). "Concerning stroke severity, several studies have shown that circulating Igf1 and Igfbp3 were reduced after stroke and that post-stroke Igf1 and Igfbp3 serum levels were inversely associated with infarct volume." (PMID 35557964, 2022). "Circulating level of IGFBP3 has been shown to be associated with hypertension, stroke, carotid atherosclerosis and several cardiovascular disease risk factors." (PMID 35087571, 2021). "High concentrations of circulating IGFBP-3 are associated with reduced risk of ischemic stoke and improved functional outcomes following stroke events." (PMID 33631000, 2021). "A recent study showed that not only low levels of IGF-1 were associated with an unfavourable functional outcome of stroke but also the level of insulin-like growth factor binding protein-3 (IGFBP-3)." (PMID 28373915, 2017). "In contrast, other studies reported an association between lower IGFBP3 levels and stroke, coronary events and CVD mortality." (PMID 29100429, 2017). "Given the role of cGP in regulating IGF-1 function, we evaluated the changes in cGP, IGF-1, and IGFBP-3 concentrations in plasma and brain tissues, as well as their association with clinical outcomes in patients with metabolic hypertension, stroke, age-related cognitive impairment, PD, and AD." (PMID 36770687, 2023). "Moreover, rs2854744 polymorphisms in IGFBP3 were associated with a decreased risk of stroke in the patients with coronary artery disease of the Chinese population." (PMID 29100429, 2017). "Specific cohorts have demonstrated a substantial reduction of 25% in IGF-1 levels and a 40% reduction in IGFBP-3 levels in stroke survivors, compared to healthy controls, indicating a severe deficit in anabolic signaling." (PMID 41598337, 2026). "The findings of lowered IGF-I and IGFBP-3 levels in the hip fracture group were similar to findings from previous studies in hip fracture cohorts, as well as in stroke patients." (PMID 39769198, 2024). "A prior study reported that low levels of IGFBP3 were predictive of worse functional outcome at one-year post-stroke based on modified Rankin scores." (PMID 37280551, 2023). "Compared with the control participants, the plasma concentrations of IGFBP-3 and cGP were lower in stroke patients at the time of hospital admission, and the concentration of IGF-1 was similar." (PMID 36770687, 2023). "Prior to stroke, basal paracrine and endocrine Igf1 and Igfbp3 levels were unchanged, and endogenous regulation of Igf1 and Igfbp3 occurs later after stroke." (PMID 35557964, 2022). "Insulin-like growth factor 1 (Igf1) and insulin-like growth factor binding protein 3 (Igfbp3) are endocrine and paracrine factors that influence stroke occurrence, severity, and recovery." (PMID 35557964, 2022). "In this study, we evaluated the effects of zinc finger protein 580 (Zfp580) on endocrine and paracrine Igf1 and Igfbp3 after stroke." (PMID 35557964, 2022). "We demonstrate in this study that Zfp580 interacts via Igf1 and Igfbp3 signaling with mechanisms relevant to stroke outcome." (PMID 35557964, 2022). "We determined the expression levels 2 days after 45 min MCAo in Zfp580 knockout mice to determine if Zfp580 has an effect on the paracrine cerebral Igf1 and Igfbp3 regulation following stroke." (PMID 35557964, 2022).
Stroke (continued). "Next, we evaluated the effects of stroke on Zfp580, Igf1 and Igfbp3 expression after 60 min of transient filamentous middle cerebral artery occlusion (MCAo) for short-term regulation up to 3 days in wild-type C56/BL6 mice." (PMID 35557964, 2022). "Insulin-like growth factor 1 (Igf1) and insulin-like growth factor binding protein 3 (Igfbp3) affect stroke occurrence and severity, as well as stroke recovery." (PMID 35557964, 2022). "With this study, we identified Zfp580 as a novel modulator of Igf1 and Igfbp3, which differentially steers paracrine cerebral and endocrine systemic responses after stroke, leading to induced Igf1 signaling." (PMID 35557964, 2022). "An inverse relationship exists between stroke risk and functional outcomes following strokes and IGF-1 and IGFBP-3 levels." (PMID 35547443, 2022). "Since IGFBP-3 is a major circulating IGFBP, which binds >75% of serum IGFs, we next measured IGFBP-3 levels in brain, serum, liver, and spleen at 2d and 5d post stroke." (PMID 27905989, 2016). "To investigate whether endogenous cGP is associated with this self-made recovery in stroke patients, we evaluated plasma concentrations of cGP, IGF-1, and IGFBP-3 at the onset of stroke and 3 months post-stroke recovery." (PMID 36770687, 2023). "In conclusion, Zfp580 differentially controls paracrine and endocrine Igf1 and Igfbp3 after stroke." (PMID 35557964, 2022). "Thus, Zfp580 deletion resulted in reduced paracrine cerebral Igf1 and Igfbp3 expression, increased endocrine Igf1 blood levels, and consecutively increased Igf1/Igfbp3 molar ratios 2 days after stroke." (PMID 35557964, 2022). "Therewith a reduction of paracrine cerebral Igfbp3 as a result of genomic ablation of Zfp580 may be beneficial for stroke recovery." (PMID 35557964, 2022). "Additionally, reduced paracrine cerebral Igfbp3 increases the amount of active unbound Igf1 in the brain, which is known to improve outcome after stroke." (PMID 35557964, 2022). "In humans, growing evidence shows effects of endocrine Igf1 and Igfbp3 after stroke." (PMID 35557964, 2022). "In summary, the effects of Igf1 and Igfbp3 on stroke outcome may be affected by their temporal and spatial regulation." (PMID 35557964, 2022). "However, after stroke, genomic ablation of Zfp580 led to a strongly reduced induction of paracrine Igf1 and Igfbp3 expression, whereas endocrine circulating Igf1 was increased." (PMID 35557964, 2022). "Interestingly, the directionality of our findings are opposite to this study, which may offer a unique relationship between IGFBP3 and cognition in stroke patients specifically." (PMID 37280551, 2023). "Thus, early induction of Zfp580 might inhibit Igf1 and Igfbp3 expression in the acute phase following stroke, but lowering Zfp580 after 3 days may allow Igf1 and Igfbp3 expression through disinhibition." (PMID 35557964, 2022). "Therefore, Zfp580 acts by Igf1 and Igfbp3 on mechanisms highly relevant for stroke outcome." (PMID 35557964, 2022). "Furthermore, serum IGFBP3 could represent a biomarker for post-stroke outcome and functional recovery." (PMID 32742258, 2020). "In parallel, insulin‐like growth factor binding protein‐3 (IGFBP‐3) modulates the bioavailability, transportation, and localization of insulin‐like growth factor‐I (IGF‐I), in animal stroke models especially when administered intranasally." (PMID 28961383, 2017). "A study found that stroke patients and high IGF1/IGFBP-3 ratios had better outcomes." (PMID 37358957, 2023). "The reduction of plasma IGFBP-3 in stroke patients could be a positive response to increase the amount of bioavailable IGF-1 in the circulation, whereas the low plasma cGP suggests a reduction of bioavailable IGF-1 in circulation during the onset of stroke." (PMID 36770687, 2023). "Similarly, NaB did not affect IGFBP3 expression either at 2 or 5 days post stroke in serum, liver, and spleen." (PMID 27905989, 2016).
Hyperglycemia (16 papers, 2009 to 2024). An increased concentration of glucose in the blood. "The goal of this study was to investigate whether IGFBP-3 inhibits monocyte-endothelial cell adhesion associated with hyperglycemia." (PMID 23592916, 2013). "This dysbiosis leads to reduced levels of TUDCA and CARN, which in turn alleviate their inhibition on the synthesis of IGFBP-3 and the expression of IL-6, ultimately resulting in hyperglycemia and related vasculopathy." (PMID 39206042, 2024). "It is known that IGFBP-3 is involved in hyperglycemia, glucose intolerance, and IR, but these effects cannot be explained by circulating free IGF-1 levels." (PMID 29112142, 2017). "In this study, we found that miR-15b in REC significantly increased the levels of IGFBP-3 in hyperglycemia." (PMID 25888955, 2015). "A relationship between increased levels of IGFBP-3 and hyperglycaemia has been suggested." (PMID 26906713, 2016). "Moreover, we found that miR-15b and miR-16 increased the levels of IGFBP-3, whose expression was decreased in hyperglycemia." (PMID 25888955, 2015). "Mice with oxygen-induced retinopathy alone versus oxygen-induced retinopathy plus streptozotocin-induced hyperglycemia/hypoinsulinemia were assessed for glucose, insulin, IGF1, IGFBP1, and IGFBP3 in blood and liver." (PMID 33004691, 2020). "Overexpression of miR-15b and/or miR-16 reduced TNFα and SOCS3 levels, while increasing insulin-like growth factor binding protein-3 (IGFBP-3) levels and the phosphorylation of insulin receptor (IR)Tyr1150/1151 in REC cultured in hyperglycemia." (PMID 25888955, 2015). "That suggests that miR-15b may directly or indirectly target IGFBP-3, which contributed to the reduced signaling of TNFα and SOCS3, as well as increased IRTyr1150/1151 phosphorylation to protect REC in hyperglycemia." (PMID 25888955, 2015).